GFRA2 (GDNF family receptor alpha 2)
Description:
Receptor for neurturin (NRTN), a growth factor that supports the survival of sympathetic neurons. NRTN-binding leads to autophosphorylation and activation of the RET receptor. Also able to mediate GDNF signaling through the RET tyrosine kinase receptor. [Isoform 2]: Participates in NRTN-induced 'Ser-727' phosphorylation of STAT3.
Synonyms: NRTNR-alpha; GDNFRB; RETL2; TRNR2; NTNRA
Tractability: Antibody: its Gene Ontology location is reachable by antibodies, with high confidence; UniProt places it where antibodies can reach, with medium confidence; UniProt predicts a signal peptide or a membrane-spanning region; the Human Protein Atlas places it where antibodies can reach. PROTAC: its protein half-life has been measured.
Target class: Membrane receptor
Gene: Protein-coding gene on chromosome 8 (21,690,398 to 21,812,370, reverse strand). Ensembl gene ENSG00000168546.
Subcellular location: Cell membrane
Subcellular location (Human Protein Atlas): Plasma membrane; Vesicles
Pathways (Reactome):
Developmental Biology: NCAM1 interactions; RET signaling
Signal Transduction: RAF/MAP kinase cascade
Gene Ontology:
Molecular function: glial cell-derived neurotrophic factor receptor activity; heparan sulfate binding; signaling receptor activity
Biological process: glial cell-derived neurotrophic factor receptor signaling pathway; cell surface receptor protein tyrosine kinase signaling pathway; nervous system development
Cellular component: plasma membrane; external side of plasma membrane; extrinsic component of membrane; receptor complex
Genetic constraint (gnomAD): Loss-of-function variants: 14 observed, 31.5 expected, observed/expected ratio (o/e) 0.44, 90% interval 0.29 to 0.69. The synonymous counts are far from expectation, so gnomAD's model fits this gene poorly and the ratio says little. Missense variants: 615 observed, 559.32 expected, observed/expected ratio (o/e) 1.1, 90% interval 1.03 to 1.17. Synonymous variants: 280 observed, 223.07 expected, observed/expected ratio (o/e) 1.26, 90% interval 1.14 to 1.39.
Homologues: Orthologues: chimpanzee GFRA2 (99% identical), macaque GFRA2 (99% identical), pig GFRA2 (95% identical), rat Gfra2 (95% identical), mouse Gfra2 (94% identical), guinea pig GFRA2 (93% identical), dog GFRA2 (79% identical), rabbit GFRA2 (69% identical), tropical clawed frog gfra2 (51% identical), zebrafish gfra2a (51% identical), zebrafish gfra2b (41% identical), Drosophila melanogaster Gfrl (26% identical), and 1 more. Paralogues in human: GFRA1 (45% identical), GFRA3 (27% identical), GFRA4 (21% identical), GFRAL (16% identical).
Diseases named in the same sentence as GFRA2 in open-access papers:
GFRA2 is named in the same sentence as 36 diseases in open-access papers, as found by Europe PMC text mining. Sharing a sentence is not in itself a finding about the gene and the disease. The quoted sentences say what the papers report.
neuroblastoma (5 papers, 2017 to 2022). Neuroblastoma (NB) is the most common solid, extracranial childhood tumor. "GFRα2 is upregulated in neuroblastoma cells and tissues, and its overexpression promotes neuroblastoma cell proliferation." (PMID 35582425, 2022). "Additionally, GFRα2 has been proposed as a potential target for antibody-/CAR T cell-based therapies against neuroblastoma." (PMID 34716856, 2022). "In human neuroblastoma cells and tissues, GFRA2 was upregulated." (PMID 33691689, 2021). "Consequently, GFRα2 promotes neuroblastoma cell proliferation by activating the PI3K/AKT pathway." (PMID 35582425, 2022). "GFRA2 interacts with PTEN, activates the PI3K/AKT pathway, and promotes neuroblastoma cell proliferation." (PMID 35646712, 2022). "Specifically, we found that, for MYCN amplified neuroblastoma, pairwise expression of ACVR2B or anaplastic lymphoma kinase (ALK) with GFRA3, GFRA2, Cadherin 24, or with one another provided the strongest hits." (PMID 28871274, 2017). "For MYCN, non-amplified stage 4 neuroblastoma, neurotrophic tyrosine kinase 1, or ALK paired with GFRA2, GFRA3, SSK1, GPR173, or with one another provided the most promising paired-hits." (PMID 28871274, 2017).
melanoma (4 papers, 2010 to 2022). A malignant, usually aggressive tumor composed of atypical, neoplastic melanocytes. "The microarray results indicated that microenvironmental cues can trigger switching of melanoma cells to a neural stem cell-like pattern, as six genes related to neural stem cell and neural stem cell niche biology were upregulated: SOX2, ID4, GFRA2, S100A4, LGI4, and GJB1." (PMID 25642713, 2015).
diabetes (2 papers, 2015 to 2018). "The analysis provided support that SNPs next to GFRA2 in the Chr8p21.3 may be associated with neuropathic pain in diabetes." (PMID 24974787, 2015).
schizophrenia (2 papers, 2017 to 2022). A major psychotic disorder characterized by abnormalities in the perception or expression of reality. "A recent study found evidence for genetic associations between GFRA1 and 3 and schizophrenia, as well as evidence for GFRA2 variants modulating the therapeutic response to clozapine." (PMID 29066960, 2017).
thyroid cancer (2 papers, 2021 to 2024). "We found that other circulating thyroid-specific targets such as TPO, IYD, TG, and GFRA2 cfRNA fell accordingly post-treatment for thyroid cancer, and could be potential biomarkers to reflect thyroid mass." (PMID 34512731, 2021). "Subsequently, Bulk-seq results indicated differential expression of GFRA2 and LILRA2 genes in thyroid cancer." (PMID 39906670, 2024). "In DEG analysis, significant changes were observed in the expression of GFRA2 and LILRA2 genes in patients with thyroid cancer." (PMID 39906670, 2024). "Some patients with thyroid cancer did not shed TPO cfRNA into the circulation and had measurable circulating TG, GFRA2, IYD cfRNA levels instead." (PMID 34512731, 2021).
atherosclerosis (1 paper, 2022). A disease characterized by the build-up of fatty material and calcium deposition in the arterial wall resulting in partial or complete occlusion of the arterial lumen. "In addition, cluster 0 expressed Serpinf1, involved in ossification and osteoblast differentiation, Hsd11b1, shown to exacerbate atherosclerosis, Pex5l, expressed in macrophages and Gfra2 in monocytes, as well as cystatin C, associated with coronary artery calcification." (PMID 35163719, 2022).
colon adenocarcinoma (1 paper, 2020). "In colon adenocarcinoma (COAD), GFRA2 showed the highest average ΔPCC in the group-specific network." (PMID 32854705, 2020).
Failure to thrive (1 paper, 2009). Failure to thrive (FTT) refers to a child whose physical growth is substantially below the norm. "Interestingly, GFRa2-deficient mice display a significant failure to thrive after weaning although the involvement of pituitary function in this phenotype has not been addressed." (PMID 19283075, 2009).
hepatocellular carcinoma (1 paper, 2015). A malignant tumor that arises from hepatocytes. "Independent of the research on GFRA2, miR-557, miR-765 and miR-17-3p all have been reported to associate with hepatocellular carcinoma." (PMID 25707620, 2015).
liver cancer (1 paper, 2022). An epithelial or non-epithelial malignant neoplasm that arises from the liver. "CHRNE, GFRA2, GFRA3, and GRIN2D may serve as potential biomarker for liver cancer prognosis or immune response." (PMID 35646712, 2022).
Osteopenia (1 paper, 2022). Osteopenia is a term to define bone density that is not normal but also not as low as osteoporosis. "Mechanistically, sclerostin inhibition in exercised Gfra2−/− mice normalized BFR, strength, and trabecular thickness, highlighting the relevance of sclerostin in the osteopenia of Gfra2−/− mice." (PMID 35276096, 2022).
pancreatic cancer (1 paper, 2021). "Similarly, a high expression level of GFRA2 leads to PTEN inactivation and then promotes tumor cell growth and chemoresistance in pancreatic cancer." (PMID 33691689, 2021).
papillary thyroid cancer (1 paper, 2021). "GFRA2 was found to be highly expressed in brain and thyroid tissue, and it was enriched in papillary thyroid cancer from the TCGA dataset." (PMID 34512731, 2021).
peripheral nerve lesion (1 paper, 2011). "GFRα2 is not the only sensory neuron growth factor receptor that is decreased following injury; both p75 and TrkA are somewhat decreased following peripheral nerve lesion, whereas both TrkB and TrkC have been reported to increase." (PMID 22216140, 2011).
pituitary tumor (1 paper, 2017). A benign or malignant neoplasm affecting the pituitary gland. "GFRα2 (from the GDNF family receptor α) has recently been described as a pituitary stem/progenitor marker, and found differentially expressed in pituitary tumors with a different biological behavior." (PMID 28526811, 2017).
synucleinopathies (1 paper, 2022). "Finally, transcripts known to be involved in Tau- and synucleinopathies include IGLON5, CAV1, GFRA2, SYNGR3, and SLC6A3, with the latter being particularly interesting as its genetic variants lead to Parkinsonism-dystonia infantile (PKDYS) syndrome." (PMID 35883433, 2022).
thyroid (1 paper, 2021). "The 11 selected thyroid-specific RNA transcripts (TPO, TG, GFRA2, IYD, PDE8B, WDR86, C16orf89, DGKI, DIO2, TSHR, and PAX8) were amplified from healthy volunteers and thyroid patients." (PMID 34512731, 2021).
viral infection (1 paper, 2020). "Therefore, although macrophages constitutively express GFRα2, the signalling component, RET, is induced by stimuli associated with viral infection." (PMID 33020210, 2020).
tumor (7 papers, 2017 to 2022). "Tumors, via the expression of GFRα1, GFRα2, GFRα3, respond to molecules released by nerves and, in an autocrine fashion, to molecules released by the tumor itself and these interactions are likely amplified in the tumor microenvironment." (PMID 32252363, 2020). "Therefore, a cell-type specific GFRα2/GFRα3 ratio could indeed determine the tumor promoting vs. tumor suppressing behavior of RET." (PMID 34716856, 2022). "We searched for neuronal receptors on human lung-resident macrophages and found a specific sequence of steps leading to formation of a GFRα2-RET-NRTN complex that was amplified in lung macrophages from chronic smokers and tumour tissue." (PMID 33020210, 2020). "However, in our analysis, GFRA2 exhibited an anti-tumor effect, while GFRA3 exerted a pro-tumor effect." (PMID 35646712, 2022). "It is suggested that GFRA2 may have the same effects on ESCC, as another tumor type in the digestive system." (PMID 33691689, 2021). "The lack of strong ALK and GFRA2 expression at the protein level highlights the need to validate analysis at the RNA level with appropriate proteomic characterization of the tumor type being studied." (PMID 28871274, 2017).
cancer (3 papers, 2022 to 2024). A tumor composed of atypical neoplastic, often pleomorphic cells that invade other tissues. "Among them, ephrin receptor EPHA4, actin binding LIM-proteins ABLIM1 and ABLIM2, semaphorin SEMA7A and glial neurotrophic factor GFRA2 genes, which are involved in axon guidance, are commonly repressed in cancer cells by DiPRO1 and SIX1." (PMID 39009887, 2024). "GDNF family receptor alpha 2 (GFRA2) plays an important role in immune cells and intermediate monocytes in cancer." (PMID 35114976, 2022). "GFRA2 and GFRA3 were glial cell line-derived neurotrophic factor (GDNF) receptors, and previous studies have suggested their participation in cancer." (PMID 35646712, 2022).
respiratory disease (1 paper, 2020). "GFRα2, RET, and MMP2 mRNA expression was analysed in lung macrophages from patients with COPD compared with patients with no underlying respiratory disease." (PMID 33020210, 2020).
GFRA2 also shares sentences with these, for which no sentence is quoted: adenoma (1 paper); Anxiety (1); astrocytoma (1); bacterial infection (1); bone cancer (1); cognitive decline (1); dementia (1); diabetic neuropathy (1); frontotemporal dementia (1); glioma (1); leukemia (1); mental disorder (1); osteoarthritis (1); osteomyelitis (1); Sciatica (1).